SATB1 (SATB homeobox 1)
Diseases named in the same sentence as SATB1 in open-access papers (continued):
Sharing a sentence is not in itself a finding about the gene and the disease.
pancreatic cancer (18 papers, 2014 to 2025). "According to reports, SDF-1 secreted by CAF stimulated the malignant progression of pancreatic cancer and gemcitabine-resistance, which is partly caused by the paracrine regulation of SATB-1 in pancreatic cancer." (PMID 35651786, 2022). "Our results revealed that the SDF-1/CXCR4/SATB-1 axis is vital to acceleration of the malignant progression and the gemcitabine resistance of pancreatic cancer cells and is associated with poor prognosis in PDAC patients." (PMID 30337520, 2018). "Additionally, elevated SATB1 expression is associated with shorter survival times in patients with pancreatic cancer." (PMID 40071088, 2025). "Finally, it was demonstrated that in pancreatic cancer an elevated SATB1 expression was associated with a shorter survival time of the patients." (PMID 31450715, 2019). "Expression of SATB1 is associated with poor prognosis in pancreatobiliary type adenocarcinomas, and predicts response to adjuvant treatment in both intestinal type and pancreatobiliary type periampullary adenocarcinomas, including pancreatic cancer." (PMID 25323550, 2014). "Additionally, the proteinatlas.org indicates that the loss of SATB1 or weak expression in tumor tissue was associated with worse overall survival for renal cell carcinoma and pancreatic cancer, while a higher expression is associated with longer overall survival." (PMID 34961766, 2021). "SATB1 is overexpressed in pancreatic cancer, playing a critical role in promoting cancer cell proliferation and invasion." (PMID 40071088, 2025). "SATB-1 overexpression in pancreatic cancer cells facilitates a positive feedback loop that maintains CAF pro-cancer phenotypes." (PMID 37217855, 2023). "SDF-1 secreted by CAFs reportedly promotes the development of pancreatic cancer and gemcitabine resistance via SATB-1 expression upregulation in tumor cells." (PMID 37217855, 2023). "The expression of SATB-1 in pancreatic cancer was regulated by SDF-1 secreted by CAF, which helps to maintain the characteristics of CAF and form a mutually beneficial feedback loop." (PMID 35651786, 2022). "For example, SDF-1 secreted by CAFs triggered malignant progression and gemcitabine resistance in pancreatic cancer by enhancing the expression of special AT-rich sequence-binding protein-1 (SATB-1) in cancer cells." (PMID 34852849, 2021). "One group demonstrated that CAF-secreted SDF-1 drives gemcitabine resistance in pancreatic cancer by forming a positive feedback loop that drives paracrine induction of SATB-1 in the pancreatic cancer cells." (PMID 34646829, 2021). "SDF-1 secreted by fibroblasts activates SATB-1 in pancreatic cancer cells, which in turn sustains tumour progression." (PMID 33671588, 2021). "For instance, CAF-secreted SDF-1 upregulates the expression of special AT-rich sequence-binding protein-1 (SATB-1) in pancreatic cancer cells, which not only sustains pancreatic tumor growth but also mediates gemcitabine resistance." (PMID 33553157, 2020). "In pancreatic cancer, SATB1 was found to be overexpressed and to promote cancer cell proliferation and invasion." (PMID 31450715, 2019). "CAF-secreted SDF-1 upregulated the expression of SATB-1 in pancreatic cancer cells, which contributed to the maintenance of CAF properties, forming a reciprocal feedback loop." (PMID 30337520, 2018). "Together with the data presented above, these results suggested that CAFs induced the gemcitabine resistance in pancreatic cancer cells by upregulation of SATB-1 via CAF-secreted SDF-1." (PMID 30337520, 2018). "In conclusion, we demonstrated that SDF-1-positive CAFs were significant in malignant progression and gemcitabine resistance, partially owing to paracrine induction of SATB-1 in pancreatic cancer cells." (PMID 30337520, 2018). "In this study, we revealed that the expression of SATB-1 mediated the gemcitabine sensibility of pancreatic cancer cells." (PMID 30337520, 2018).
pancreatic cancer (continued). "Our data also indicated CAFs highly secreted SDF-1 compared with NAFs, which specifically binds to CXCR4 in pancreatic cancer cells and subsequently upregulates the expression of SATB-1 in pancreatic cancer cells." (PMID 30337520, 2018). "In this study, we demonstrated that SDF-1, also known as C-X-C motif chemokine 12 (CXCL12), secreted by CAFs upregulated SATB-1 expression in pancreatic cancer cells via the SDF-1/CXCR4 axis." (PMID 30337520, 2018). "We cultured CAFs with CM from either control pancreatic cancer cells or SATB-1-silenced pancreatic cancer cells and analyzed the α-SMA and FAP expression levels in CAFs." (PMID 30337520, 2018). "In conclusion, these data demonstrated that CAFs upregulated the expression level of SATB-1 in pancreatic cancer cells through the SDF-1/CXCR4 axis." (PMID 30337520, 2018). "To investigate the clinical relevance of the SDF-1/SATB-1 axis in pancreatic cancer, we analyzed the expression levels of SDF-1 and SATB-1 protein in 243 paraffin-embedded human PDAC samples by immunohistochemistry." (PMID 30337520, 2018). "In summary, these results manifested that CAFs can significantly upregulate the expression of SATB-1 in pancreatic cancer cells and that SATB-1 is markedly increased in both pancreatic cancerous tissues and pancreatic cancer cell lines." (PMID 30337520, 2018). "In our study, we found that SATB-1 expression in pancreatic cancer cells mediated the maintenance of CAF properties and the activation of CAFs from NAFs." (PMID 30337520, 2018). "Our study provides the first evidence of the association of the SDF-1/CXCR4/SATB-1 axis with PDAC malignant progression and CAF maintenance, suggesting a potential new target of clinical interventions for pancreatic cancer patients." (PMID 30337520, 2018). "As reported in our study, we found that SATB-1 is overexpressed in PDAC tissues and pancreatic cancer cell lines, and SATB-1 is upregulated by CAFs-secreted SDF-1." (PMID 30337520, 2018). "Downregulation of SATB-1 decreased the IC50 values in pancreatic cancer cells, thus indicating that SATB-1 played an active role in promoting gemcitabine resistance in pancreatic cancer cells." (PMID 30337520, 2018). "Overexpression of SATB-1 in pancreatic cancer cells was vital for the maintenance of CAF-like properties, thus forming a regulatory feedback loop in the tumor microenvironment." (PMID 30337520, 2018). "Here, we show that SDF-1 secreted by CAFs stimulates malignant progression and gemcitabine resistance in pancreatic cancer, partially owing to paracrine induction of SATB-1 in pancreatic cancer cells." (PMID 30337520, 2018). "Then, NAFs were also treated with conditioned medium from pancreatic cancer cells with different SATB-1 expression." (PMID 30337520, 2018). "In vitro study demonstrated that SATB1 can promote pancreatic cancer cell growth and invasion through the induction of oncogene MYC mRNA and protein expression." (PMID 28430598, 2017). "SATB1 knockdown has been shown to significantly inhibit cell proliferation, colony formation, and non-adherent growth while reducing the migratory capacity of pancreatic cancer cells in vitro." (PMID 40071088, 2025). "SATB1′s overexpression was also observed in liver and pancreatic cancers." (PMID 31450715, 2019). "However, the specific roles of SATB-1 in CAFs promoted pancreatic cancer progression are poorly elucidated." (PMID 30337520, 2018). "In this study, we show that SDF-1, a characteristic C-C chemokine released by tumor-associated fibroblasts, can prominently upregulate the expression of SATB-1 and subsequently contribute to malignant progression and gemcitabine resistance of pancreatic cancer cells." (PMID 30337520, 2018). "In addition, we found that overexpression of SATB-1 in pancreatic cancer cells participated in the process of gemcitabine resistance." (PMID 30337520, 2018).
pancreatic cancer (continued). "However, the clinical and biological function of SATB-1 in pancreatic cancer deserves further investigation, especially in the tumor environment." (PMID 30337520, 2018). "In summary, these findings demonstrated that the SDF-1/CXCR4/SATB-1 axis may be a potential new target of clinical interventions for pancreatic cancer patients." (PMID 30337520, 2018). "Finally, we investigated the clinical correlations between SDF-1 and SATB-1 in human pancreatic cancer specimens." (PMID 30337520, 2018). "In addition, we have also found that overexpression of SATB-1 in pancreatic cancer cells in turn plays a vital role in maintaining the local supportive function of CAFs, indicating the formation of a SATB-1-centered positive feedback loop in pancreatic cancer." (PMID 30337520, 2018). "Our clinical specimens IHC staining found that SATB-1 expression is relative with SDF-1 expression, suggesting SATB-1 expression in pancreatic cancer cells may be upregulated by SDF-1 derived from CAFs in the stromal." (PMID 30337520, 2018). "Our study emerged that CAF-promoted SATB-1 dysregulation in pancreatic cancer cells may contribute to gemcitabine resistance by some mechanism that requires further research." (PMID 30337520, 2018). "Besides, experimental models were utilized to validate the value of SATB-1 in pancreatic cancer, which mainly included the proliferation, migration, and invasion of pancreatic cancer cells in vitro." (PMID 30337520, 2018). "As CAFs exert significant impact on the metastatic hallmark of pancreatic cancer, we wondered whether overexpression of SATB-1 in pancreatic cancer cells could influence the fibroblast phenotype." (PMID 30337520, 2018). "In terms of cancer type, 9 studies contained or included data of SATB1 expression in CRC patients, 4 studies with data on SATB1 expression in GC patients, 2 studies with SATB1 expression in other types of gastrointestinal cancer, more specifically in esophageal cancer and pancreatic cancer." (PMID 28430598, 2017). "However, the specific role of SATB-1 in pancreatic cancer remains elusive." (PMID 30337520, 2018). "Therefore, we examined whether the SDF-1/CXCR4 axis regulates the SATB-1 expression level in pancreatic cancer cells." (PMID 30337520, 2018). "SATB-1 was verified to be overexpressed in human pancreatic cancer tissues and cell lines by quantitative real-time PCR, western blot, and immunohistochemical staining, which correlated with tumor progression and clinical prognosis in pancreatic cancer patients." (PMID 30337520, 2018). "Hence, we chose SATB-1 as a gene of interest and set out to determine whether SATB-1 facilitates malignant progression of pancreatic cancer and participates in the crosstalk between tumor cells and CAFs." (PMID 30337520, 2018). "CAFs-secreted cytokines may promote the expression of SATB-1 in pancreatic cancer cells." (PMID 30337520, 2018). "The interaction between CAFs and pancreatic cancer cells was found to be a positive feedback loop, with SDF-1 promoting SATB-1 expression in the cancer cells, which in turn contributed to the maintenance of CAF phenotypes in the stroma." (PMID 33808627, 2021). "qRT-PCR and western blotting showed that SATB-1 was upregulated in PANC-1 and SW1990 pancreatic cancer cells only when co-cultured with CAFs, validating our microarray results." (PMID 30337520, 2018). "Importantly, the authors found a clinical correlation of SATB-1 and SDF-1 in human pancreatic cancer specimens." (PMID 33671588, 2021). "Taken together, our present work provides solid evidence for reciprocal interactions between CAFs and pancreatic cancer cells, shedding new light on the utilization of the SDF-1/CXCR4/SATB-1 axis as a potential therapeutic target for the treatment of pancreatic cancer." (PMID 30337520, 2018). "Finally, we examined the clinical correlation of SATB-1 and SDF-1 in human pancreatic cancer specimens." (PMID 30337520, 2018).
pancreatic cancer (continued). "Then, we found that SDF-1-induced SATB-1 upregulation inhibits proliferation, migration, and invasion of pancreatic cancer cells, and conditioned medium from SW1990 and PANC-1 cells expressing SATB-1 maintains the properties of older CAFs, forming a SATB-1-centered positive feedback loop." (PMID 30337520, 2018).
colon carcinoma (12 papers, 2013 to 2025). "Special AT-rich sequence-binding protein-1 (SATB1) abnormalities are associated with colon cancer." (PMID 35884607, 2022). "ELFN1-AS1 drives colon cancer cells to proliferate and invade by adjusting the miR-191-5p/SATB1 axis." (PMID 35265722, 2022). "When USP47 was defective, the transcriptional activity of the SATB1 target gene was impaired, and the proliferation of colon cancer cells was inhibited in the mouse model." (PMID 35884607, 2022). "Professor Du confirmed that the lncRNA ELFN1-AS1 promotes colon cancer cell proliferation and invasion by modulating the miR-191-5p/SATB1 axis in colon cells." (PMID 35846130, 2022). "SATB2 acts as a tumor suppressor in laryngeal squamous cell carcinoma and colon cancer, whereas SATB1 promotes the progression of numerous types of cancers." (PMID 26701851, 2016). "SATB1 expression in COLO205 colon cancer cells was downregulated by statins via posttranslational modifications of SATB1 protein which led to targeting it for proteolytic degradation." (PMID 25874491, 2015). "Moreover, hydrophobic statins such as fluvastatin and simvastatin have been reported to downregulate SATB1 at the posttranslational level in a time- and dose-dependent manner in human colon cancer cells." (PMID 40890836, 2025). "Studies in breast and colon cancer showed over expression of SATB1 could promote tumor cell growth and inhibit apoptosis." (PMID 23379909, 2013). "Additionally, reversible ubiquitination of SATB1 by USP47 and SMURF2 promotes colon cancer proliferation." (PMID 41208974, 2025).
glioma (12 papers, 2012 to 2025). A benign or malignant brain and spinal cord tumor that arises from glial cells (astrocytes, oligodendrocytes, ependymal cells). "Phosphorylated special AT-rich sequence-binding protein 1 (SATB1) is a TF associated with the progression and poor prognosis of glioma." (PMID 36231068, 2022). "Collectively, our findings indicated for the first time that SATB1 was overexpressed in human glioma, and SATB1 expression in human glioma was associated with clinicopathological factors and prognosis." (PMID 22839214, 2012). "Nano-HAPs alone inhibited glioma cell proliferation, but their combination with SATB1 shRNA enhanced these effects, demonstrating the potential of this approach for glioma therapy." (PMID 40071088, 2025). "utilized nano-HAPs to deliver SATB1 shRNA, significantly inhibiting growth, invasion, and angiogenesis in human glioma U251 cells both in vitro and in vivo." (PMID 40071088, 2025). "Our investigation provides evidence that hsa_circ_0010889 downregulation can reduce glioma proliferation and invasion via miR-590-5p/SATB1 signaling mediated by the regulation of aerobic glycolysis." (PMID 37540226, 2023). "Western blot detection show that SATB1 overexpression or miR-590-5p inhibition restored glioma cell EMT-related protein expression post silencing of hsa_circ_0010889." (PMID 37540226, 2023). "Using EdU we found that SATB1 overexpression or miR-590-5p inhibition restored glioma cell proliferation ability in both LN229 and U251 cells post hsa_circ_0010889 silencing." (PMID 37540226, 2023). "Again, using EdU detection we found that overexpression of SATB1 restored glioma cell proliferation in both LN229 and U251 cells post miR-590-5p overexpression." (PMID 37540226, 2023). "SATB1 overexpression or miR-590-5p inhibition reversed glioma cells proliferation and migration post-silencing of hsa_circ_0010889." (PMID 37540226, 2023). "Transwell assays for the detection of migration showed that SATB1 overexpression or miR-590-5p suppression restored glioma cell migration ability in LN229 and U251 cells post silencing of hsa_circ_0010889." (PMID 37540226, 2023). "SATB1 overexpression also restored migratory ability post hsa_circ_0010889 silencing, suggesting that removing the effect of hsa_circ_0010889 can inhibit glioma progression by promotion miR-590-5p and inhibiting SATB1 expression." (PMID 37540226, 2023). "Downregulation of hsa_circ_0010889 inhibited glioma invasion and proliferation in both in vitro and in vivo experiments and luciferase report assays found that miR-590-5p and SATB1 were downstream targets for hsa_circ_0010889." (PMID 37540226, 2023). "Transwell assays also showed that overexpression of SATB1 restored glioma cell migration ability in both U251 and LN229 cells after overexpression of miR-590-5p." (PMID 37540226, 2023). "Taken together, our study demonstrates that hsa_circ_0010889 downregulation inhibits glioma progression through the miR-590-5p/SATB1 axis." (PMID 37540226, 2023). "Previous experiments have reported the promoting role of miR-21 in glioma, and upregulation of SATB1 and CPEB3 is associated with the development and progression of glioma." (PMID 35069683, 2021). "The survival analysis further suggested the regulatory correlation: elevated FAM18A-AS1 and miR-21 were associated with poor prognosis in glioma, and low expression of BCL7A, SATB1, and CPEB3 was associated with favorable prognosis." (PMID 35069683, 2021). "The most significantly mutated genes include FBXW7 (encoding WNT signaling molecule) in B-cell lymphoma, SATB1 (functioning in chromatin remodeling) in T-cell lymphoma, and CALD1 (encoding an actin and myosin binding protein) in glioma." (PMID 34344882, 2021). "In glioma cells, SATB1 was found to even act as a repressor of HER2, since SATB1 knockdown led to an induction of HER2 expression." (PMID 33374770, 2020).